PFKFB4 (6-phosphofructo-2-kinase/fructose-2,6-biphosphatase 4)
Diseases named in the same sentence as PFKFB4 in open-access papers (continued):
Sharing a sentence is not in itself a finding about the gene and the disease.
clear-cell renal cell carcinoma (4 papers, 2021 to 2025). "PFKFB4 promotes chemoresistance in clear-cell renal cell carcinoma." (PMID 37919747, 2023). "PFKFB4 is involved in chemoresistance to sunitinib in clear-cell renal cell carcinoma." (PMID 37919747, 2023).
colon cancer (4 papers, 2010 to 2024). "PFKFB4 has been induced by hypoxia in multiple cancer cell lines and overexpressed in matched human lung, breast, and colon tumor tissues relative to normal tissues from the same patients." (PMID 39595571, 2024). "Clearly, this study may provide relevant ideas and evidence for the role of PFKFB4 in the anti-colon cancer mechanism of 5-FU." (PMID 37770581, 2023). "PFKFB4 is strongly induced by hypoxia through an hypoxia inducible factor 1 alpha (HIF1A) subunit dependent mechanism, and might contribute significantly to the Warburg effect observed in malignant gastric, pancreatic, breast and colon tumors." (PMID 20059769, 2010).
brain cancer (3 papers, 2021 to 2025). A primary or metastatic malignant neoplasm affecting the brain. "Studies showed that loss of PFKFB4 in brain cancer stem-like cells promoted cell death while inhibited lactate secretion, which was essential for the maintain of the brain cancer stem-cells stemness." (PMID 33593309, 2021). "This is consistent with studies showing that PFKFB4 and HMOX1 are overexpressed in various cancer types and are linked to poorer prognosis and reduced survival rates in brain cancer patients." (PMID 40739397, 2025).
hepatic cancer (3 papers, 2018 to 2022). "Similarly, sulforaphane, an isothiocyanate commonly found in broccoli and other cruciferous vegetables, was shown to induce apoptosis in hepatic cancer cells through inhibition of 6-phosphofructo-2-kinase/fructose-2,6-biphosphatase 4 (PFKFB4)." (PMID 35890106, 2022). "The lncRNA FIRRE promotes liver cancer cell proliferation and glycolysis through improving CREB-mediated transcription as well as PFKFB4 expression." (PMID 35874626, 2022). "In hepatic cancer cell lines, sulforaphane-induced apoptosis was shown to decrease PFKFB4 protein expression and glucose consumption whereas HIF-1α induced PFKFB4 expression under hypoxic conditions." (PMID 30234009, 2018).
lymph node metastasis (3 papers, 2021 to 2023). "High PFKFB4 expression was also associated with poor DSS in oral cancer patients with lymph node metastasis." (PMID 37919747, 2023). "High PFKFB4 expression was associated with a shorter survival in oral cancer patients with advanced lymph node metastasis and clinicopathological stages." (PMID 37919747, 2023). "We found that PFKFB4 expression in tumor tissues was significantly higher than that in normal tissues and high PFKFB4 expression was associated with a short PFI in oral cancer patients with lymph node metastasis and late pathological stages." (PMID 37919747, 2023).
breast tumor (2 papers, 2021 to 2022). "Interaction of PFKFB4 with steroid receptor coactivator-3 (SRC-3) protein has been found as a key regulatory mechanism in breast tumor." (PMID 33593309, 2021). "Notably, these alternate roles can contribute to tumor progression with another glycolytic enzyme, 6-phosphofructo-2-kinase/fructose-2,6-bisphosphatase 4 (PFKFB4) shown to phosphorylate SRC-3 resulting in its transcriptional activation which was shown to drive breast tumor growth and metastasis." (PMID 36476366, 2022).
hepatoblastoma (2 papers, 2024 to 2025). Hepatoblastoma (HB) is a malignant hepatic tumor and is the most common pediatric liver cancer. "Our study identifies DNMT3B and PFKFB4 as genes associated with metastatic characteristics in hepatoblastoma, suggesting them as potential biomarkers that require further investigation." (PMID 39595571, 2024). "This study identified the dual overexpression of PFKFB4 and DNMT3B in hepatoblastoma patients at risk of metastasis (high-risk CHIC classification)." (PMID 39595571, 2024). "We used a univariate analysis to demonstrate that the meta.score, derived from the combined expression of DNMT3B and PFKFB4, can predict metastasis status in hepatoblastoma tumors." (PMID 39595571, 2024). "A meta.score, computed from the combined tumor expression of DNMT3B and PFKFB4, was confirmed as an independent adverse predictor of metastatic status in hepatoblastoma." (PMID 39595571, 2024). "While our study identified DNMT3B and PFKFB4 as individual predictive biomarkers of metastasis in hepatoblastoma, it is also possible that these two proteins interact or influence each other’s functions." (PMID 39595571, 2024). "Our study, which utilized the Mammalian Metabolic Enzyme Database, led to the development of a metabolic score based on the combined expression of DNMT3B and PFKFB4 in hepatoblastoma." (PMID 39595571, 2024). "In this study, we identified dual overexpression of PFKFB4 and DNMT3B in hepatoblastoma patient samples with metastatic risk (high-risk CHIC stratification), based on the metabolic enzyme expression program of hepatoblastoma tumors." (PMID 39595571, 2024). "In conclusion, our study has identified DNMT3B and PFKFB4 as potential individual biomarkers of metastasis in hepatoblastoma." (PMID 39595571, 2024). "The combined tumor expression of DNMT3B and PFKFB4 was used to compute a metabolic score, which was validated as an independent predictor of metastatic status in hepatoblastoma." (PMID 39595571, 2024). "Notably, the transcriptional expression of DNMT3B, followed by PFKFB4 and SOD3, was identified as the most strongly correlated with positive metastatic status in hepatoblastoma." (PMID 39595571, 2024).
metastatic tumors (2 papers, 2019 to 2024). "In luminal cancers, the Warburg pathway enzyme PFKFB4 acts as a molecular fulcrum that couples sugar metabolism to transcriptional activation by stimulating the ER co-activator SRC-3 to promote aggressive metastatic tumors." (PMID 31801490, 2019). "Furthermore, the Warburg pathway enzyme PFKFB4 has been found to couple sugar metabolism with transcriptional activation by stimulating SRC-3 and promoting aggressive metastatic tumors." (PMID 39595571, 2024).
neuroblastoma (2 papers, 2019 to 2021). Neuroblastoma (NB) is the most common solid, extracranial childhood tumor. "Undoubtedly, attention should be paid to the fact that in the case of neuroblastoma solely high expression of isoenzyme PFKFB3 correlates with poor prognosis whereas solely high expression of PFKFB4 is a positive prognostic factor for these patients." (PMID 31754349, 2019). "What is more, our analysis indicates worryingly, that application of PFKFB4 inhibitors for neuroblastoma patients characterized by overexpression of both isoenzymes could even have a negative impact on the patient prognosis." (PMID 31754349, 2019). "In order to determine the influence of PFKFB3/4 co-expression on survival rate, the gene expression data were downloaded (GSE62564) and neuroblastoma patients were divided on four groups based on the median PFKFB3/PFKFB4 expression, as described in Materials and Methods." (PMID 31754349, 2019). "What’s more, it seems that in neuroblastoma the prognostic value of PFK-II may be dependent on the relation between PFKFB3 and PFKFB4 isoenzyme expression, indicating that further studies analyzing the role of both cancer specific PFK-II isoenzymes are highly desired." (PMID 31754349, 2019). "However, neuroblastomas with both high PFKFB3 expression and high PFKFB4 co-expression showed a 1.69 hazard ratio, indicating that PFKFB4 may offset negative effects caused by PFKFB3." (PMID 34831136, 2021). "The worst survival prognosis could be observed for the patients with the dominant PFKFB3 expression (G3 group), which clearly indicates that low expression of PFKFB4, and high expression of PFKFB3 at the same time has a negative impact on the survival of neuroblastoma patients." (PMID 31754349, 2019).
oral cancer (2 papers, 2023 to 2025). "The overexpression of PFKFB3 and PFKFB4 was associated with low survival in oral cancer patients and was involved in cell growth/migration and chemoresistance/cancer stemness in OSCC cells, respectively." (PMID 37919747, 2023). "The co-expressions of PFKFB3/cell cycle or EMT markers and PFKFB4/stemness markers were associated with poor prognosis in oral cancer patients." (PMID 37919747, 2023). "We discovered that PFKFB3 expression in tumor tissues was slightly higher than that in tumor adjacent normal tissues but that PFKFB4 expression was significantly higher in the tumor tissues of oral cancer patients." (PMID 37919747, 2023). "Our results indicate that PFKFB3 and PFKFB4 expression levels have different effects on the prognosis of oral cancer patients with different clinicopathological outcomes." (PMID 37919747, 2023). "Our current study supports the clinical relevance and biological functions of PFKFB3 and PFKFB4 in oral cancer." (PMID 37919747, 2023). "In the present study, we revealed that the expression of PFKFB4 was higher in the tumor tissues of oral cancer patients than in tumor-adjacent normal tissues." (PMID 37919747, 2023). "The co-expressions of PFKFB3/cell cycle or EMT markers and PFKFB4/stemness markers in oral cancer patients were also related to poor prognosis." (PMID 37919747, 2023). "High PFKFB3 and PFKFB4 expression had different effects on the prognosis of oral cancer patients with different clinicopathological outcomes." (PMID 37919747, 2023). "Since cancer stemness and drug resistance confer to survival of cancer patients, our results suggest that elevated PFKFB4 might modulate signaling pathway required for drug resistance and cancer stemness, which in turn to contribute worse survival of oral cancer patients." (PMID 37919747, 2023). "We found that oral cancer patients with high expression of PFKFB3 and PFKFB4 had poor prognosis." (PMID 37919747, 2023). "Furthermore, oral cancer patients with co-expressions of PFKFB3/cell cycle or EMT markers and PFKFB4/stemness markers had poor prognosis." (PMID 37919747, 2023).
ovarian carcinoma (2 papers, 2017 to 2019). A malignant neoplasm originating from the surface ovarian epithelium. "This work has uncovered a novel function of the enzymes PFKFB3 and PFKFB4 in ovarian cancer cells during mitotic arrest." (PMID 28152500, 2017). "Our high content siRNA screen successfully identified PFKFB4 as an important regulator of ovarian cancer cell survival following mitotic arrest by paclitaxel." (PMID 28152500, 2017). "While numerous studies have identified the importance of PFKFB3 and PFKFB4 in cancer cell survival, we are the first to investigate the impact of their depletion in ovarian cancer cells and identify their importance during mitotic arrest." (PMID 28152500, 2017). "A high-content siRNA screen to detect novel metabolic targets in mitotically arrested ovarian cancer cells identified the glycolytic enzyme PFKFB4." (PMID 28152500, 2017). "Moreover, we have identified a previously unrecognised role of PFKFB3 and PFKFB4 in mitotically arrested ovarian cancer cell survival." (PMID 28152500, 2017). "This discrepancy might be due to PFKFB3 and PFKFB4 having distinct roles in ovarian cancer cells." (PMID 28152500, 2017). "This work has identified a previously unrecognised role of PFKFB4 in mitotically arrested ovarian cancer cell survival and supports the notion that combining mitotic-targeted therapies with glycolytic inhibitors may potentiate the effects of antimitotics in ovarian cancer." (PMID 28152500, 2017). "As ovarian cancer cells do not appear to be energetically stressed after PFKFB4 depletion, we hypothesised that the levels of reactive oxygen species (ROS) may be increased after PFKFB4 depletion." (PMID 28152500, 2017). "Moreover, the fact that A2780 cells remain unaffected by PFKFB4 depletion demonstrates the specificity of this vulnerability and that it is not universal across all ovarian cancer cell lines." (PMID 28152500, 2017). "We observed a significant increase in mitotic cell death following PFKFB4 depletion compared to the non-targeting control (p=0.0056, two-way ANOVA multiple comparison), indicating that PFKFB4 is important for ovarian cancer cell survival during prolonged mitosis." (PMID 28152500, 2017).
prostate tumor (2 papers, 2013 to 2022). "We found that prostate tumor protein samples expressed higher levels of PFKFB4 than normal samples." (PMID 36115843, 2022).
acute monocytic leukemia (1 paper, 2021). Acute monoblastic leukemia (AML-M5), is one of the most common subtypes of acute myeloid leukemia (AML) that is either comprised of more than 80% of monoblasts (AML-M5a) or 30-80% monoblasts with (pro)monocytic differentiation (AML-M5b). "PFKFB4 was critical for the survival of acute monocytic leukemia (AMoL) cells, serving as a downstream target of MLL through the putative E2F6 binding site in the promoter of the PFKFB4 gene, which might be a potent therapeutic target in AMoL." (PMID 33593309, 2021).
Alzheimer disease (1 paper, 2024). A progressive, neurodegenerative disease characterized by loss of function and death of nerve cells in several areas of the brain leading to loss of cognitive function such as memory and language. "There are also studies on the relationship between genes and cognitive function that show that five genes, PFKFB4, PDK3, KIAA0319L, CEBPD, and PHC2T, have the potential to recognize Alzheimer’s disease." (PMID 39328989, 2024).
autoimmune disease (1 paper, 2022). A disorder resulting from loss of function or tissue destruction of an organ or multiple organs, arising from humoral or cellular immune responses of the individual to their own tissue constituents. "Since people with seasonal influenza infections and autoimmune diseases can also develop CRS, we explored PFKFB4 expression in these diseases." (PMID 35902861, 2022). "Our study is the first to report that the expression of PFKFB4 increases under these conditions and is a driving force in triggering cytokine release through the involvement of glycolytic pathway activity in CAR T-cells, viral infections and autoimmune diseases." (PMID 35902861, 2022).
benign prostatic hyperplasia (1 paper, 2020). A non-cancerous nodular enlargement of the prostate gland. "Prostate tissue samples including PCa tissue, carcinoma-adjacent tissue and benign prostatic hyperplasia (BPH) tissue specimens were evaluated for PFKFB4 expression using immunohistochemistry." (PMID 32487245, 2020).
cervical squamous cell carcinoma (1 paper, 2019). A squamous cell carcinoma arising from the cervical epithelium. "Interestingly, in cervical squamous cell carcinoma we revealed that patients with high expression of both, PFKFB3 and PFKFB4 have significantly worse overall survival in comparison to the ones with low expression." (PMID 31754349, 2019).
colon adenocarcinoma (1 paper, 2023). "Colon adenocarcinoma (COAD) is a common malignant tumor, and the role of the protein PFKFB4 in glycolysis and pentose phosphate pathways is crucial." (PMID 37770581, 2023).
COVID-19 (1 paper, 2022). A disease caused by infection with severe acute respiratory syndrome coronavirus 2. "In general, PFKFB4 gene expression was significantly up-regulated in COVID-19 patients compared to healthy donors." (PMID 35902861, 2022). "In addition, we noted that PFKFB4 gene expression in asymptomatic people infected with SARS-CoV-2 and in COVID-19 convalescent people were stable and at the same level as in healthy subjects." (PMID 35902861, 2022).
endometriosis (1 paper, 2022). The growth of functional endometrial tissue in anatomic sites outside the uterine body. "The findings show that PIM2 expression was positively correlated with PFKFB4 in endometriosis in vivo." (PMID 36109523, 2022). "To verify the effect of the PFKFB4 Thr140 site on endometriosis cells, we knocked out endogenous PFKFB4 expression and re-expressed them in endometriosis cells above." (PMID 36109523, 2022). "Then, we analyzed the change regions between PIM2 and PFKFB4 in endometriosis cells by confocal analysis and found that PFKFB4 protein level expression was decreased when shPIM2 was used to knock down PIM2 expression." (PMID 36109523, 2022). "The clone forming ability and proliferation ability of endometriosis cells also increased significantly when PFKFB4 was overexpressed." (PMID 36109523, 2022). "Consistently, the glucose consumption and Lactic acid production were reduced in endometriosis cells when PFKFB4 was knockdown." (PMID 36109523, 2022). "Simultaneously, PFKFB4 expression was decreased when PIM2 expression was knocked down by shPIM2 in endometriosis cells." (PMID 36109523, 2022). "In contrast, the migration ability, clonogenic ability, and cell proliferation ability of endometriosis cells decreased significantly when we knocked out the expression of PFKFB4 in endometriosis cells." (PMID 36109523, 2022). "Interestingly, glucose consumption and Lactic acid production were upregulated in endometriosis cells when PFKFB4 was overexpressed." (PMID 36109523, 2022). "Interestingly, when we knocked down PFKFB4 in endometriosis cells by shPFKFB4 and then overexpressed PIM2 protein levels, the glucose consumption, and lactate production were not clearly changed." (PMID 36109523, 2022). "Moreover, PIM2 expression was really corresponding prevalent with PFKFB4 in endometriosis in vivo." (PMID 36109523, 2022). "Therefore, PIM2 and PFKFB4 Thr140 phosphorylation promotes glycolysis in endometriosis." (PMID 36109523, 2022). "Moreover, PIM2 expression is positively correlated with PFKFB4 in endometriosis in vivo." (PMID 36109523, 2022). "To further determine that PIM2 can regulate PFKFB4 in vivo, we utilized PIM2-knockout endometrial tissue as a donor to construct a mouse model of endometriosis." (PMID 36109523, 2022).
HIV-1 infection (1 paper, 2022). The type species of lentivirus and the etiologic agent of acquired immunodeficiency syndrome (AIDS). "HIF-1α accumulation was consistent with the temporal induction of a gene set of hypoxia responsive genes (e.g., CA9, PFKFB4, and VEGF) in our transcriptome analysis and the idea that HIF-1α enhances HIV-1 infection by binding hypoxia-responsive elements (HRE) present at the 5′-LTR." (PMID 36298843, 2022).
influenza (1 paper, 2022). An acute viral infection of the respiratory tract, occurring in isolated cases, in epidemics, or in pandemics; it is caused by serologically different strains of viruses (influenzaviruses) designated A, B, and C, has a 3-day incubation period, and usually lasts for 3 to 10 days. "We found that PFKFB4 expression was up-regulated in influenza-infected (H1N1, H3N2, Influenza B) individuals in the early stages of infection, and decreased in the recovery stage." (PMID 35902861, 2022).
kidney cancer (1 paper, 2021). Primary or metastatic malignant neoplasm involving the kidney. "Through in silico analyses of ChIP-seq dataset Cistrome we identified 7 candidate TFs among which HIF1A was reported to transcribe PFKFB4 in other cancers but was not validated in kidney cancer." (PMID 34593007, 2021).
metastatic melanoma (1 paper, 2022). A melanoma that has spread from its primary site to another anatomic site. "Using human metastatic melanoma cell lines with high PFKFB4 expression, we show that PFKFB4 activity is required for active cell migration in several different cellular contexts, without a connection to the rate of glycolysis." (PMID 35914811, 2022). "Glycolysis regulator PFKFB4 promotes cell migration in metastatic melanoma and normal melanocytes by a non-conventional glycolysis-independent function involving ICMT, RAS, and AKT signaling." (PMID 35914811, 2022).